MMP2 (matrix metallopeptidase 2)
Diseases named in the same sentence as MMP2 in open-access papers (continued):
Sharing a sentence is not in itself a finding about the gene and the disease.
Hypertension (continued). "In a recent human study, elevated plasma MMP-9 level correlated with systolic BP, however, elevation of plasma MMP-2 and -10 had better correlation with hypertension-induced renal damage." (PMID 24159376, 2013). "Contrary to our prediction, we observed that MMP2 activity was increased in the aorta harvested from rats with AngII-induced hypertension." (PMID 24205262, 2013). "The present study shows in a homogeneous and representative group of patients with clinically and functionally stable hypertension a good stability of MMP-2 and sTNF-R1 levels." (PMID 23008783, 2012). "There is good stability in MMP-2 and sTNF-R1 levels in a followup study of patients with stable hypertension." (PMID 23008783, 2012). "This study shows that there is good stability in MMP-2 and sTNF-R1 levels in a 12-month follow-up study of asymptomatic patients with clinically and functionally stable hypertension." (PMID 23008783, 2012). "To that end we analyzed MMP-2 as its expression is known to increase as a consequence of hypertension and vein graft preparative injury." (PMID 21777461, 2011). "Mean amniotic fluid MMP-2 levels were significantly higher in women who developed a hypertensive disorder in pregnancy compared with normotensive pregnancies (22.3 ± 1.3 ng/ml versus 17.2 ± 0.6 ng/ml, respectively; P < 0.0004)." (PMID 19698156, 2009). "We showed significantly higher levels of MMP-2 in amniotic fluid of women who developed a hypertensive disorder compared to normotensive women." (PMID 19698156, 2009). "Given the growing evidence linking MMP-2 activity with hypertension-related TOD, understanding the genetic underpinnings of MMP-2 in RH could offer new insights into disease mechanisms and therapeutic targets." (PMID 40311090, 2025). "However, clinical studies have shown that in patients with essential hypertension, MMP-2 levels were raised after 6 months of treatment with felodipine or amlodipine." (PMID 38610612, 2024). "Additionally, the treatment with another MRA—eplerenonon—in an animal model of hypertensive HF resulted in the inhibition of MMP-2, MMP-12 and MMP-13 activities, as well as improvement of myocardial remodeling." (PMID 36835040, 2023). "At present, no study has explored the correlation between rs14070 in MMP2 and IS susceptibility, only found that rs14070 was positively correlated with the incidence of hypertension caused by urinary cadmium." (PMID 35959401, 2022). "Additionally, a significant relationship between increased CRP, MMP-9, and MMP-2 levels and systolic hypertension and arterial stiffness was demonstrated." (PMID 35873099, 2022). "However, increased expression and activity of MMP-2 is involved in cardiovascular diseases such as atherosclerosis, aneurysm, hypertension, and HF." (PMID 35893744, 2022). "Besides inflammation, increased levels of MMP2 critically contribute to aortic and cardiac remodeling in hypertension." (PMID 35133978, 2022). "Another study with MMP-2−/− mice infused with angiotensin II showed that MMP-2 deletion did not affect the severity of hypertension but caused cardiac hypertrophy to develop earlier and to a greater extent than in wild-type animals." (PMID 35893744, 2022). "Particularly MMP-2 and MMP-9 have been linked to the development of hypertension." (PMID 35774422, 2022). "Additionally, plasma level of MMP-2 was upregulated in patients with COVID-19 and hypertension, although still less than in healthy controls." (PMID 36142454, 2022). "Finally, another mechanism that contributes to the VSMC phenotype switch in hypertension is the MMP-2-induced degradation of calponin-1, as recently shown." (PMID 33923477, 2021). "Inorganic nitrite or nitrate supplementation may also exert antioxidant effects and diminish MMP-2 activity and the vascular remodeling of hypertension." (PMID 33923477, 2021).
Hypertension (continued). "MMP-2 and MMP-9 are also responsible for activating cytokines, such as transforming growth factor-β (TGF-β), which are involved in collagen accumulation and profibrotic alterations in remodeling that are associated with hypertension." (PMID 33923477, 2021). "Moreover, high total cfDNA was significantly associated with adverse maternal-fetal outcomes (high blood pressure, low platelet count, preterm delivery, FGR) and with high circulating prohypertensive factors (sFLT-1, sEndoglin, MMP-2)." (PMID 33429954, 2021). "The results of our study may indicate that MMP-2 inhibition is therapeutically applicable during the development of hypertension, while in developed, stabilized and uncomplicated hypertension, systemic MMP-2 and MMP-9 inhibition may not be desirable." (PMID 33023122, 2020). "This could point to a more important role of MMP-2 in the development of hypertension in comparison with MMP-9 in this particular model." (PMID 33023122, 2020). "We found a significantly higher concentration of MMP-2 in patients with clinical features of severe PE, confirming the participation of MMP-2 in the second stage of PE implementation, i.e., endothelial damage, development of arterial hypertension, and multiple-organ damage." (PMID 33381317, 2020). "The expression and activity of MMP-2 in plasma increase in patients with left ventricular pressure overload such as hypertension and aortic stenosis, and the level of MMP-2 is positively correlated with the development of left ventricular hypertrophy and heart failure." (PMID 31825469, 2019). "An additional risk factor such as hypertension did not cause significant changes in the levels of MMP-2, MMP-9, and TIMP-4." (PMID 31781384, 2019). "Hypertension activates MMP-2 through mechanical and oxidative stress." (PMID 31781384, 2019). "Interestingly, the authors of the present study first reported l-NAME-induced hypertension and vascular remodeling in rats in which there was an up-regulation of MMP-2 and MMP-9 protein expression in response to oxidative stress." (PMID 30347737, 2018). "The decreased MMP-2 activity in the hypertensive patients is involved in the vascular remodeling in the hypertension condition, showing a potential link relating to vascular compliance and hypertension in menopause by the increased of collagen content as well as decreased MMP activity." (PMID 30133537, 2018). "However, the plasma level of Mmp2 from hypertensive patients has been demonstrated to be both increased and decreased, why its specific role in hypertension is yet to be elucidated." (PMID 28880918, 2017). "MMP2 and MMP9 are two major matrix metalloproteinases and involve in digesting extracellular matrix in placenta; loss of function of MMP2 and MMP9 are associated with un-remodeling spiral vessel, hypertension, compromised trophoblast invasion and preeclampsia during pregnancy." (PMID 28959722, 2017). "On the other hand, MMP-2 polymorphisms (g.–1306C>T and g.–735C>T) do not seem to be associated with hypertensive disorders during pregnancy nor pharmacological response." (PMID 28726716, 2017). "MMP-2 may participate in the pathogenesis of hypertension and through direct interaction with vasoactive peptides." (PMID 27490532, 2016). "Despite the increased evidence of the important role of matrix metalloproteinases(MMP-9 and MMP‐2) in the pathophysiology of hypertension, the profile of thesemolecules in resistant hypertension (RHTN) remains unknown." (PMID 26039662, 2015). "This suggests a potential role for MMP-2 in hypertension-related vascular remodeling." (PMID 23950935, 2013). "Therefore, the aims of the present study were to analyze MMP-2 and sTNF-R1 variability during a 12-month followup, in a cohort of stable hypertensive patients." (PMID 23008783, 2012). "None of the tested SNPs were associated with hypertension, indicating that the MMP-2 effect on recovery was not mediated by its role on vascular structure (data not shown)." (PMID 20222942, 2010).
Hypertension (continued). "MMP-2, MMP-9, and ADAM17 have been implicated in the degradation of the endothelial barrier, leading to the increased permeability of the endothelium and the recruitment of inflammatory cells, which further promotes progression of vascular remodeling and hypertension." (PMID 40492135, 2025). "In our opinion, the decrease in MMP-2 activity or its protein levels may be caused by the reduction of mean arterial pressure due to ACF in hypertensive TGR rats and adaptation of the myocardium to hypertension." (PMID 36834901, 2023). "Furthermore, by reducing MMP2 (Matrix Metalloproteinase 2) activity and oxidative stress, chronic treatment with quercetin (10 mg/kg/day) ameliorates hypertension-induced coronary hypertrophic remodeling in renovascular hypertensive rats, even if it does not reduce cardiac dysfunction." (PMID 37298188, 2023). "Whereas inhibition of pro-MMP2 activation might have been sufficient to protect from aortic remodeling and progression of hypertension, additional direct antiinflammatory actions of DEL-1 were most likely critical to ensuring protection from cardiac remodeling." (PMID 35133978, 2022). "Therefore, inhibition of MMP2 by DEL-1 in aorta may represent an important mechanism of action in protection from at least vascular remodeling during hypertension." (PMID 35133978, 2022). "Conversely, immunohistochemistry measurements of fibrosis indicators MMP2 and MMP9 in the PBS group showed significantly more expression compared to the control level due to the stimulation of hypertension." (PMID 41551933, 2026). "Curcumin has been shown to inhibit MMP-2 and MMP-9 activity, reduce inflammation, and improve endothelial function in animal models of hypertension." (PMID 40492135, 2025). "It has been demonstrated that MMP-2 and MMP-9 specifically contribute to the development of hypertension by cleaving extracellular matrix proteins, which results in vascular stiffness and elevated blood pressure." (PMID 40492135, 2025). "For example, knock out of MMP-2 and MMP-9 by CRISPR/Cas9 system in animal models results in reduced hypertensive responses, highlighting its critical role in the development of hypertension." (PMID 40492135, 2025). "Resveratrol, a polyphenol found in grapes and berries, has been shown to inhibit MMP-2 and MMP-9 activity, reduce oxidative stress, and improve vascular function in animal models of hypertension." (PMID 40492135, 2025). "In an Ang II-induced rat hypertension model, ERS induction increased aortic collagen content, fibrosis, and MMP-2 activity, whereas the inhibition of ER stress decreased blood pressure, collagen content, and fibrosis, while improving vascular functions." (PMID 38282657, 2024). "Increased expression or activity of MMP-2 and/or MMP-9 proteins has been most frequently observed in dysglycemia, hypertension, oxidized LDL and high LDL levels, and inflammation." (PMID 39596317, 2024). "CUR treatment prevented morphological alterations in the aorta wall found in 2K-1C hypertensive rats and significantly reduced matrix metalloproteinase-2 (MMP-2) and matrix metalloproteinase-9 (MMP-9) levels in the aortic walls generated by 2K-1C hypertension." (PMID 36770715, 2023). "In addition, studies demonstrate that increased MMP-2 activity may contribute to eutrophic and hypertrophic remodeling because MMP-2 can participate in the development of vascular tone and induce hypertension-induced proteolysis, attenuating vasodilator signaling." (PMID 37372128, 2023). "MMP-2 and MMP-3 are considered as enzymes initiating hypertension-related remodeling of arteries and large arteries walls stiffening." (PMID 36835040, 2023). "First, the dependent variable was edema volume, MMP-2 level or variables (age, mRS, GCS, haematoma volume, NIHSS, plasma potassium level, hypertension, alcohol consumption, blood leucocyte count, current smoking) was independent variables, respectively." (PMID 38090262, 2023).
Hypertension (continued). "Papers that focus on the effect of NBL on MMP-2 levels have been performed on cardiac and vascular tissues, as NBL is indicated in hypertension." (PMID 36902508, 2023). "Regarding this, the activation of MMP-2 and MMP-9 was directly involved in the vascular remodeling observed in hypertension." (PMID 35625532, 2022). "More importantly, increased MMP2 and MMP9 were found to increase the risks of cardiovascular disease and clinical hypertension in children with obesity." (PMID 36034923, 2022). "TIMP-3 can inhibit MMP-2, MMP-3, and MMP-9 which regulate ECM structure and vascular remodelling and consequently affect hypertension-induced stroke." (PMID 35444693, 2022). "The expressions of MMP-2 and MMP-9, which are involved in the development of hypertension, were significantly decreased in aortas from CP and MS rats." (PMID 35774422, 2022). "Verapamil has been shown to reduce MMP-2 activity by decreasing oxidative stress and calpain-1 that regulates MMP-2 activity in a model of HF induced by hypertension." (PMID 35893744, 2022). "In the PPI network, we observed that IL-6, CCL2, IL-1β, MMP-2, and MMP-9 were the hub targets of GZD for improving hypertension." (PMID 33906674, 2021). "The results suggest that the upregulation of the expression of TGF‐β1, TNF‐α, MMP‐2, and MMP‐9 contributes to the development of hypertension, proteinuria, and glomerular and tubular injury in Dahl S rats." (PMID 33377622, 2021). "Lacerda L, Faria AP, Fontana V, Moreno H, Sandrim V. Role of MMP-2 and MMP-9 in resistance to drug therapy in patients with resistant hypertension." (PMID 32267335, 2020). "MMP-2 and MMP-9 also play roles in the remodeling of blood vessels at the stage of placental formation and in the development of hypertension due to damage to basement membrane vasculature." (PMID 33381317, 2020). "Later in pregnancy, an elevation in MMP-2 and MMP-9 induces abnormal release of vasoactive factors conditioning hypertension." (PMID 28726716, 2017). "Further research is needed to investigate how glycemic control and antihypertensive drug therapy can affect concentrations of ET-1, MMP-2, MMP-9, and TIMPs, and what the relationship is of these molecules with the pathogenesis of hypertension in T2D." (PMID 27490532, 2016). "In this study, also a correlation between higher levels of metalloproteinase MMP-2 as well as higher values of MMP-2/TIMP-2 ratio and the prevalence of arterial hypertension was observed." (PMID 26843213, 2016). "Dysregulation of MMP-2 expression and impaired MMP-2 activity are involved in abnormal uteroplacental artery remodeling and trophoblastic invasion in hypertension of pregnancy." (PMID 25803859, 2015). "Our findings suggest that in addition to MMP-2 and -9, MMP-13 is also likely to regulate ECM remodeling in hypertension." (PMID 24159376, 2013). "Collectively, these data support the idea that proteasome activity contributes to AngII-induced hypertension and hypertensive aortic vascular remodeling at least in part by modulating TIMP1/2 and MMP2 function." (PMID 24205262, 2013). "Thus, we hypothesize that inhibiting Mmp2 may help prevent heart failure from hypertension." (PMID 24564975, 2013). "Mean amniotic fluid MMP-2 and TIMP-2 levels were significantly higher in women who developed a hypertensive disorder compared to normotensive women (P < 0.0004 and P < 0.01, respectively)." (PMID 19698156, 2009). "Hypertension could activate vascular MMP-2 expression as seen in angiotensin-II treated mice, whereas miR-29b-3p directly targets MMP-2 and regulates its synthesis." (PMID 36292250, 2022). "In addition to inflammation, DEL-1 overexpression inhibits the activity of matrix metallopeptidase 2 (MMP2) in the aorta, whose increase critically contributes to aortic remodeling in hypertension." (PMID 36518760, 2022). "Elevation of MMP-2 in hypertension has been proved by several studies, but studies on the mechanism of MMP-2 decrease in patients with COVID-19, are still lacking." (PMID 36142454, 2022).
Hypertension (continued). "MMP-2, elevated in TAA, also mediates angiotensin-II induced hypertension." (PMID 33807627, 2021). "Thus, we focused on the circulating levels of β1-AA alongside with myocardial MMP-2 activity in male and female SHR with an advanced stage of hypertension." (PMID 31947691, 2020). "The results showed that MMP‐2 and MMP‐9 levels in the pregnant hypertension rats were significantly reduced compared with those in the healthy pregnant rats, but such effects could be significantly rescued by TTR treatment (P < 0.05)." (PMID 32533762, 2020). "This response is also related to the extracellular matrix degradation of elastic fibers since the up-regulation of matrix metalloproteinase-2 (MMP-2) and matrix metalloproteinase-9 (MMP-9) expression in vessel tissue has been confirmed in animal models of hypertension." (PMID 30347737, 2018). "In keeping with this, we hypothesize that MMP-2 and MMP-9 are induced at the early stages of the hypertension, and this is probably favorable for alleviation of the initial vascular tensile stress." (PMID 27490532, 2016). "In addition to MMP-2 and MMP-9, we demonstrate that MMP-13 also plays a significant role in hypertension-induced renal injury." (PMID 24159376, 2013). "Alterations in specific MMPs, such as MMP-2 and MMP-9, which are gelatinases expressed on cell surfaces (MMP-2) or secreted (MMP-9) by endothelial cells and myofibroblasts influence arterial remodeling, leading to various pathological disorders that include hypertension." (PMID 35774422, 2022). "The results of our study may indicate that MMP-2 inhibition is therapeutically applicable during development of hypertension, while in developed, stabilized and uncomplicated hypertension, systemic MMP-2 and MMP-9 inhibition may not be desirable." (PMID 33023122, 2020). "Studies on mouse models of hypertension-induced cerebral microvascular hemorrhages (CMH) demonstrate that pathogenesis of the CMHs involves a weakening of the vessel wall by upregulation of MMPs or oxidative stress-dependent activation of MMPs, such as MMP2 and MMP968." (PMID 32144343, 2020). "Collectively, these data support the notion that omega-3 via suppression of β1-AA mechanistically controlled by MMP-2 may attenuate abnormal of Cx43 and PKC-ε signaling; thus, abolish arrhythmia substrate and protect rats with an advanced stage of hypertension from malignant arrhythmias." (PMID 31947691, 2020). "Experimental hypertension studies have reported that the intima and media thickness ofconduct vessels was associated with increased expression of MMP-9 and MMP-2, and thisevent could be prevented with non-selective MMP inhibitor (doxycycline)treatment." (PMID 26039662, 2015). "MMP-2 concentrations were 1.02, 1.03 and 1.05 times, and MMP-9 concentrations were 1.03, 1.06 and 1.07 times greater for 1 unit increase in log-transformed water, hair and nail arsenic concentrations, respectively, after adjusting for covariates (age, sex, BMI, smoking habit and hypertension)." (PMID 26637202, 2015). "Thus it has been suggested that plasma concentrations of MMP-2, MMP-9 and TIMP-1 could serve as markers of cardiovascular remodeling in hypertension or in type 2 diabetic patients where MMP-9 in particular is elevated." (PMID 25535075, 2014). "The theory that hypertension in pregnancy may represent a spectrum of manifestations, ranging from mild (GH) to severe symptoms (PET, sPET), may explain our results showing progressive increase in MMP-2 levels between the GH group and PET, sPET groups." (PMID 19698156, 2009). "Higher levels of MMP-2 were found in the plasma of non-pregnant patients with hypertension." (PMID 19698156, 2009). "The role of MMP-2 and MMP-9 in the etiopathogenesis of essential hypertension is documented in a number of studies, but none of them comprehensively address their age-dependent activation." (PMID 33023122, 2020).